STAT3 (signal transducer and activator of transcription 3)
Diseases named in the same sentence as STAT3 in open-access papers (continued):
Sharing a sentence is not in itself a finding about the gene and the disease.
osteosarcoma (continued). "On the one hand, it has been shown that cytoplasmic STAT3 repressed autophagy in osteosarcoma U2OS cells by inhibiting PKR activity." (PMID 31311917, 2019). "The present study provide evidence that BD has strong inhibitory effects on osteosarcoma stem cell like properties and tumor growth through repression of STAT3 signaling pathway, which suggests BD as a promising therapeutic agent for osteosarcoma." (PMID 31631559, 2019). "Regardless of pyruvate, PAM produces inhibition of relevant kinases such as AMPK or STAT3, thus revealing itself as a potential therapy against osteosarcoma." (PMID 31337843, 2019). "Our results showed SC efficacy against osteosarcoma growth and migration in vitro, and prevention of feedback activation of STAT3 induced by erlotinib both in vitro and in vivo." (PMID 31422383, 2019). "Activation of EGFR would bypass the EGFR/JAK/STAT3 axis, initiate other downstream signalling pathways, and compensate for the inactivation of STAT3, favoring osteosarcoma growth and progression." (PMID 31422383, 2019). "Following the demonstration of constitutive activation of STAT3 in neoplastic cells, pharmacologic inhibition of STAT3 was investigated in several malignancies, including osteosarcoma." (PMID 30286779, 2018). "NP treatment suppresses both expression and phosphorylation of STAT3 in addition to blocking STAT3-mediated transcription and downstream target proteins in osteosarcoma cells." (PMID 30286779, 2018). "Our data indicate that STAT3 inactivation was involved in osteosarcoma stem cells elimination of resveratrol treatment." (PMID 30356255, 2018). "In this study, we provided evidences that JAK2/STAT3 signaling inhibition was involved in resveratrol induced osteosarcoma stem cells elimination." (PMID 30356255, 2018). "In this study, we examined the effect of resveratrol on osteosarcoma stem cells and explored the underlying molecular mechanisms of JAK2/STAT3 signaling pathway." (PMID 30356255, 2018). "A recent study suggested that Apatinib promotes autophagy and induces apoptosis through VEGFR2/STAT3/BCL-2 signaling in osteosarcoma." (PMID 29490645, 2018). "Further analysis of STAT3 pathway in human osteosarcoma stem cells will provide critical proofs for optimized therapy." (PMID 30356255, 2018). "Our studies show that NP-mediated inhibition of STAT3 blocks osteosarcoma growth in vitro and in vivo." (PMID 30286779, 2018). "Our results also show that cytokine (IFN-γ)–mediated activation of STAT3 activity and STAT3-dependent transcription in osteosarcoma cells are blocked by NP." (PMID 30286779, 2018). "In this report, we showed that the STAT3 inhibitor NP induces cell death and inhibits STAT3 protein expression, phosphorylation, and transcriptional activity in osteosarcoma cells." (PMID 30286779, 2018). "Lgr4 gene expression is activated by BMP2 in osteoblastic cells or by signal transducer and activator of transcription 3 (STAT3) signalling in osteosarcoma cells." (PMID 29316729, 2018). "JAK2/STAT3 signaling blockage plays a crucial role in therapeutic effects of resveratrol treated osteosarcoma cells." (PMID 30356255, 2018). "Meanwhile, PI3K/AKT/NF-κB signaling, a downstream pathway of JAK2/STAT3, was also examined in the gradient of resveratrol treated osteosarcoma cells." (PMID 30356255, 2018). "Current findings show that NP regulates STAT3 at multiple levels and blocks both tyrosine and serine phosphorylation of STAT3 proteins in addition to decreasing its expression levels in osteosarcoma cells." (PMID 30286779, 2018). "Then we performed further investigation on the activity of JAK2/STAT3 signaling pathway in resveratrol treated osteosarcoma cells." (PMID 30356255, 2018). "The use of a specific siRNA to inhibit STAT3 expression in OS cells weakened the effects of ADSCs on osteosarcoma cell proliferation and invasion." (PMID 28423603, 2017).
osteosarcoma (continued). "In a separate study, IL-6-dependent Stat3 activation in mesenchymal stem cell-derived osteosarcoma cells protects tumor cells from drug-induced apoptosis, and promoted proliferation and metastasis." (PMID 28054649, 2017). "The Src-Stat3 pathway is persistently activated in osteosarcoma, so inhibitors of both Src and Stat3 induce caspase-3 mediated apoptosis of osteosarcoma cells." (PMID 28054649, 2017). "Based on these data, stromal ADSCs promote osteosarcoma progression by increasing STAT3 signalling-mediated MMP2/9 expression." (PMID 28423603, 2017). "In this study, the activation of Src-Stat3 signaling was observed among all tested human osteosarcoma cell lines, except NOS-1 cells that highly express AMBN." (PMID 28054649, 2017). "Taken together, our data indicate a relationship between ADSCs and osteosarcoma progression mediated by STAT3 signalling pathway activation, accompanied by increased MMP expression and decreased E-cadherin expression." (PMID 28423603, 2017). "Here, we have demonstrated that AMBN induced apoptosis and doxorubicin sensitivity, and suppressed colony formation and cell migration in osteosarcoma cells via inactivation of the Src-Stat3 pathway." (PMID 28054649, 2017). "Here we demonstrated that stable overexpression of AMBN induced apoptosis and suppressed colony formation and cell migration via the inactivation of Src-Stat3 pathway in human osteosarcoma cells." (PMID 28054649, 2017). "According to the survival curves, STAT3 inhibition prolonged the survival of mice with osteosarcoma; however, ADSC-conditioned medium decreased the survival of the animals." (PMID 28423603, 2017). "To further confirm the negative regulation of STAT3 signal in Apatinib-treated osteosarcoma cells, we focused on the effect of Apatinib in osteosarcoma cells and how STAT3 was suppressed by siRNA." (PMID 28837148, 2017). "In conclusion, the present study is the first report that 4-MD shows profound anti-cancer activity in vitro and in vivo, and also induces cell apoptosis in osteosarcoma cells by inhibiting the JAKT2/STAT3 pathway." (PMID 26755649, 2016). "Activation of STAT3 was observed in both osteosarcoma cell lines 30 minutes after incubation with MSCs CM." (PMID 27340780, 2016). "Together, these results suggest that STAT3 modulates the protective effects of MSCs on osteosarcoma cells." (PMID 27340780, 2016). "In conclusion, IL-6 and the activated STAT3 pathway represent novel targets to inhibit tumour self-seeding by CTCs, which has great potential to inhibit osteosarcoma progression and enhance survival." (PMID 26623559, 2016). "Using a drug-resistant osteosarcoma cell line, we showed that MSCs-induced STAT3 activation was similar to drug-induced STAT3 activation and that inhibition of STAT3 in both mice tumor models decreased tumor growth and prolonged overall survival." (PMID 27340780, 2016). "Using a osteosarcoma mouse model with co-injection of MSCs with Saos-2cells, we found that inhibition of STAT3 prolonged the survival time of tumor bearing mice by suppressing tumor growth and increasing the sensitivity of tumor cells to doxorubicin." (PMID 27340780, 2016). "We previously demonstrated that IL-6, a major activator of STAT3 signaling, plays an important role in the interaction between MSCs and osteosarcoma cells." (PMID 27340780, 2016). "Our data indicated that Eag1 promotes osteosarcoma proliferation and migration, at least in part, by targeting STAT3-VEGF pathway." (PMID 26783521, 2015). "STAT3 inhibition by RNA interference induces inhibition of proliferation and apoptosis enhancement in osteosarcoma cells." (PMID 25146150, 2014). "Constitutive activation of the STAT3 pathway has recently been shown in several malignancies, especially osteosarcoma." (PMID 25146150, 2014). "The small molecules, LLL12 and FLLL32, inhibit STAT3 phosphorylation and exhibit potent growth suppressive activity in osteosarcoma cells and tumor growth in mice." (PMID 25146150, 2014).
osteosarcoma (continued). "A high level of expression of STAT3 by IHC in 76 biopsies of patients with an osteosarcoma was a poor prognostic factor for both overall survival and disease-free survival in univariate and multivariate analysis." (PMID 25146150, 2014). "The novel curcumin analog FLLL32 decreases STAT3 DNA binding activity and expression, and induces apoptosis in osteosarcoma cell lines." (PMID 25146150, 2014). "The down-regulation of STAT3 by miR-125b suppresses in vitro proliferation and migration of osteosarcoma cells." (PMID 25146150, 2014). "Two studies of murine osteosarcoma have confirmed that three transcription factors: Nanog, Oct3/4 and STAT3, are involved in maintaining self-renewal and pluripotency of ES cells." (PMID 24893164, 2014). "Other stem cell markers such as STAT3 and Sox4 were also strongly expressed in MSCs, while angiopoietin-1 was highly expressed in osteosarcoma cells." (PMID 22852096, 2012). "Our data indicate that STAT3 inhibition effectively suppresses growth of OS-1 osteosarcoma xenografts." (PMID 22530037, 2012). "OSM activates JAK2 and STAT3 upon binding to its receptor in many cells including murine, rat, and human osteoblastic cells and osteosarcoma cell lines." (PMID 21481226, 2011). "The data is consistent with previous studies that Stat3 pathways play an important role in not only drug sensitive but also drug resistant osteosarcoma cells." (PMID 20459702, 2010). "Constitutive activation of Stat3 pathway has been found in many cancer cells including osteosarcoma." (PMID 20459702, 2010). "Osteosarcoma tissues showed heterogeneous expression of Stat3 mediated antiapoptotic proteins and Pgp1." (PMID 20459702, 2010). "After identifying CDDO-Me as an inhibitor of Stat3 nuclear translocation in osteosarcoma cells, the effect of CDDO-Me on Stat3 phosphorylation was examined in osteosarcoma drug sensitive and MDR cell lines." (PMID 20459702, 2010). "The activation of signal transducer and activator of transcription 3 (Stat3) pathway correlates with tumor growth, survival, drug resistance and poor prognosis in osteosarcoma." (PMID 20459702, 2010). "In osteosarcoma tissues, Stat3 was overexpressed in all of the samples and pStat3 was overexpressed in 7 out of 8 (88%) samples." (PMID 20459702, 2010). "Stat3, pStat3 and Stat3 targeted antiapoptotic proteins are over expressed in drug resistance osteosarcoma cells." (PMID 20459702, 2010). "CDDO-Me significantly inhibited Stat3 phosphorylation, Stat3 nuclear translocation and induced apoptosis in osteosarcoma." (PMID 20459702, 2010). "To explore the potential therapeutic values of this pathway, we assessed both the expression and the activation of Stat3 pathway in several pairs of multidrug resistant (MDR) osteosarcoma cell lines, and tissues." (PMID 20459702, 2010). "More recent work investigating the potential role of STAT3 activation in pediatric sarcomas including osteosarcoma (OSA), rhabdomyosarcoma, and Ewing sarcoma demonstrated that constitutive STAT3 phosphorylation occurs in a high percentage of these tumors." (PMID 19284568, 2009). "The most detailed work done to date investigating the role of STAT3 in human sarcomas revealed elevated levels of pSTAT3 in a subset of pediatric sarcomas which included osteosarcomas (OSAs) as well as in OSA cancer stem cells." (PMID 19284568, 2009). "STAT3 phosphorylation has been demonstrated in a subset of human osteosarcoma (OSA) tissues and cell lines." (PMID 19284568, 2009). "Inhibition of the Stat3 pathway suppressed cell growth of osteosarcoma and rhabdomyosarcoma cell lines in vitro." (PMID 17598902, 2007). "The Stat3 pathway is involved in cell growth and survival of human rhabdomyosarcoma and osteosarcoma cells." (PMID 17598902, 2007). "Here we present evidence that activated Stat3 is detected in osteosarcoma, rhabdomyosarcoma, and soft-tissue sarcoma tissues and cell lines." (PMID 17598902, 2007).
osteosarcoma (continued). "We demonstrated that the levels of Stat3 phosphorylation is elevated in human osteosarcomas, rhabdomyosarcomas and other soft-tissue sarcomas tissues." (PMID 17598902, 2007). "Although Stat3 is known to be activated in other cancer types, Stat3 activation in osteosarcomas, rhabdomyosarcomas, and soft-tissue sarcomas is still unclear." (PMID 17598902, 2007). "This study demonstrates that Stat3 phosphorylation is elevated in human rhabdomyosarcoma, osteosarcomas and soft-tissue sarcomas." (PMID 17598902, 2007). "The percentages of p-Stat3 positive samples were 19% (21/113) of osteosarcoma, 27% (17/64) of rhabdomyosarcoma, and 15% (22/151) of other soft-tissue sarcoma samples." (PMID 17598902, 2007). "Western blots with a p-Stat3 specific antibody revealed that Stat3 was phosphorylated in several rhabdomyosarcoma, osteosarcoma, and leiomyosarcoma cell lines." (PMID 17598902, 2007). "These previous studies are consistent with our finding that the Stat3 signaling pathway is constitutively activated in rhabdomyosarcomas, osteosarcomas, and other soft-tissue sarcomas." (PMID 17598902, 2007). "Stat3 phosphorylation is elevated in 19% (21/113) of osteosarcoma, 27% (17/64) of rhabdomyosarcoma, and 15% (22/151) of other soft-tissue sarcoma tissues as well as in sarcoma cell lines." (PMID 17598902, 2007). "Stat3 phosphorylation is elevated in human rhabdomyosarcoma, osteosarcomas, and other soft-tissue sarcomas." (PMID 17598902, 2007). "Targeting DUSP3 and the EGFR/STAT3/SOX2 axis may offer a new therapeutic approach for treating osteosarcoma." (PMID 39744427, 2025). "While multidrug-resistant osteosarcoma cell lines exhibit a constitutive activated Stat3 pathway with elevated levels of p-STAT3, treatment with bardoxolone methyl inhibited cell growth and induced apoptosis in osteosarcoma cells, significantly reducing the nuclear translocation and p-STAT3." (PMID 40732256, 2025). "STAT3 plays major roles in the progression and metastasis of osteosarcoma." (PMID 40109854, 2025). "STAT3 activation is critical for survival and proliferation of osteosarcoma." (PMID 40529368, 2025). "In osteosarcoma, hsa-miR-199a-3p is significantly underexpressed; its restoration suppresses tumor cell growth and migration by directly targeting oncogenes such as Met, mTOR, and Stat3." (PMID 41154751, 2025). "Inhibition of STAT3 blocks protein synthesis and reduces tumor metastasis in osteosarcoma cells." (PMID 40109854, 2025). "Stattic, an inhibitor of STAT3, was used to treat the osteosarcoma cells." (PMID 39744427, 2025). "Similarly, STAT3 inhibition significantly altered the stemness-promoting effect of DUSP3 knockdown in osteosarcoma cells." (PMID 39744427, 2025). "Stattic, a STAT3 inhibitor, was treated with osteosarcoma cells after transfecting with shDUSP3." (PMID 39744427, 2025). "Furthermore, it has been noted that FBXO2 controls the signal transducer and activator of transcription 3 (STAT3) signaling pathway, which is essential for the growth of osteosarcoma cells." (PMID 41035649, 2025). "Moreover, the upregulation of lncRNA PVT1 has been shown to facilitate the development of osteosarcoma by activating the STAT3/GPX4 axis, thereby reducing ferroptosis and modulating GSH and ROS levels." (PMID 40403492, 2025). "STAT3 is consistently activated in multiple human tumors including osteosarcoma." (PMID 40529368, 2025). "Targeting the EGFR/STAT3/SOX2 axis may be a promising therapeutic approach for treating osteosarcoma." (PMID 39744427, 2025).
osteosarcoma (continued). "However, compared with drug-resistant osteosarcoma cells, overexpression of miR-506-3p or silencing of STAT3 decreased the expression of Bcl-2 and increased the expression of Bax, which in turn led to a decrease in the Bcl-2/Bax ratio." (PMID 38420199, 2024). "In addition, treatments with BP-1-102, a STAT3 inhibitor, abolished resistance to cisplatin, indicating that the STAT3/NRF2/GPx4 signal has a critical function in the drug resistance of osteosarcoma cells." (PMID 38539832, 2024). "Additionally, CHA can reduce STAT3 phosphorylation and STAT3 and Snail protein levels, block the STAT3/Snail pathway, inhibit the progression of osteosarcoma cells, and induce apoptosis." (PMID 39867913, 2024). "Furthermore, suppression of GPX4 and SOD2 reversed resistance to EGFR-TKIs in NSCLC and the induction of ferroptosis by impairing STAT3/Nrf2/GPx4 signaling enhances the sensitivity of osteosarcoma cells to cisplatin." (PMID 39681067, 2024). "In addition, diosmetin have been shown that it can be used to treat human osteosarcoma through STAT3/c‐Myc signal pathway." (PMID 38800967, 2024). "In addition, inhibition of JAK2/STAT3 signaling led to a decrease in the osteosarcoma stem cell marker CD133." (PMID 39206407, 2024). "Our study also confirmed that Survivin was highly expressed in osteosarcoma-resistant cells, and overexpression of miR-506-3p or silencing of STAT3 was able to inhibit Survivin expression, thereby enhancing the sensitivity of drug-resistant osteosarcoma cells to doxorubicin." (PMID 38420199, 2024). "Siglec-15 has been shown to be expressed in osteosarcoma cells and may inhibit proliferation in osteosarcoma through the signal transducer and activator of transcription 3 (STAT3/Bcl-2) pathway, while inducing apoptosis and pyroptosis." (PMID 38182638, 2024). "However, no studies have been reported on the role of miR-506-3p in the development of osteosarcoma and reversal of doxorubicin resistance by targeting STAT3." (PMID 38420199, 2024). "Inhibition of STAT3 activity had been shown to improve the chemosensitivity of osteosarcoma cells." (PMID 38420199, 2024). "Osteosarcoma cells transfected with miR-125b-5p showed higher sensitivity to doxorubicin, which was achieved by downregulation of P-pg drug transporter and suppression of signal transducer and inhibits the transcription 3 (STAT3) expression." (PMID 39679367, 2024). "Additionally, it was shown that oridonin significantly reduced the expression of MMP-2, -3, and -9 in osteosarcoma cells and, in addition, reduced the level of phosphorylation of p-STAT3 (Tyr 705) and p-STAT3 (Ser 727)." (PMID 38397437, 2024). "Studies had shown that STAT3 was highly expressed and continuously activated in osteosarcoma, which was involved in various pathological processes such as cell transformation, proliferation, tumor formation, invasion, migration, immune escape and drug resistance." (PMID 38420199, 2024). "Notably, the phosphorylation levels of STAT3 decrease in osteosarcoma cells treated with this combination therapy." (PMID 38920657, 2024). "It had been demonstrated that the inhibition of JAK2/STAT3 signaling pathway could decrease cell viability, invasion and migration of osteosarcoma cells and induced apoptosis in cancer cells." (PMID 38420199, 2024). "ErbB4 and STAT3 confer osteosarcoma chemoresistance via the inhibition of apoptosis." (PMID 37107591, 2023). "Based on previous research, we speculated that FANCD2 interacts with JAK2/STAT3 pathway to mediate osteosarcoma development." (PMID 36814203, 2023). "We found IL-6 and its downstream pathway STAT3 were activated in anlotinib-resistant osteosarcoma." (PMID 37404767, 2023). "Taken together, we indicated that FANCD2 may mediate ferroptosis in osteosarcoma by JAK2/STAT3 pathway to regulate tumor cell growth." (PMID 36814203, 2023).